CDX2 (caudal type homeobox 2)
Diseases named in the same sentence as CDX2 in open-access papers (continued):
Sharing a sentence is not in itself a finding about the gene and the disease.
tumor (continued). "The immunohistochemical report showed that tumor cells were stained positive for cytokeratin AE1/3, cytokeratin CAM5.2, chromogranin A (CgA), synaptophysin (Syn), CD56 antigen, CDX-2 and Ki-67 (approximately 30-50%)." (PMID 24884973, 2014). "CDX2 and HEPH expression are well correlated in normal and tumor tissues, and CDX2 expression is downregulated in CRC." (PMID 23812305, 2013). "Silencing the expression of EphA2 receptor also increases the expression of cdx-2 which indicates that knockdown of EphA2 either by ephrin-A1 activation or by silencing interference RNA could be potential in inhibiting the oncogenic effect of receptor EphA2 and tumor growth." (PMID 22824143, 2012). "We examined histological phenotype of tumors of AFPC or NEC containing the composite tumor by evaluating immunohistochemical expressions of MUC2, MUC5AC, MUC6, CDX2, and SOX2." (PMID 22482081, 2012). "In the composite tumor, the three components expressed SOX2, but CDX2 was expressed in the neuroendocrine component." (PMID 22482081, 2012). "Typically, PPCA demonstrates tumor cells positive for CK7, CK20, and CDX-2." (PMID 40390751, 2025). "Confirmatory immunostaining with appropriate controls performed on this case revealed that the tumor cells are positive for CDX2 and MUC2 (focal) but negative for CK5/6, S100, p16, and GCDFP15." (PMID 40438862, 2025). "Thus, we concluded that CDX2 and HTR2B, markers of the CMS2/3 and CMS4 subgroups, respectively, are present in the same tumor samples." (PMID 41034989, 2025). "We first asked whether the relationship among ATRX, HNF4A, CDX2 and LY6D expression identified in our mouse model exists in human tumour samples." (PMID 40468074, 2025). "The tumor cells were also negative for CDX2 and CK20 (colonic adenocarcinoma markers), CK7 (lung/pancreaticobiliary marker), and TTF-1 (lung marker)." (PMID 40671972, 2025). "Comparatively, a lower proportion (35/55, 63.6%) of HG tumours stained positively for CDX2, while 36.4% of HG tumours (e.g., HCT116, SW620, LIM2405 and HCC2998) were negative for CDX2 expression (P < 0.0001, Fisher’s exact test)." (PMID 40473896, 2025). "Furthermore, the expression patterns of β-catenin, CDX2, CK20, and Ki67 were found to be similar between the organoids and tumor tissues, demonstrating that organoids preserve the molecular biological characteristics of the original tissues." (PMID 40069844, 2025). "Interestingly, CDX2 and HTR2B are present in the same tumor samples, showing intratumoral cellular heterogeneity." (PMID 41034989, 2025). "Gene set enrichment analysis of IC3 identified enrichment of target genes of CDX2, a transcription factor that is highly and exclusively expressed in gut epithelium, emphasizing IC3 as a component that distinguishes tumor from adjacent normal tissue gene expression." (PMID 40410286, 2025). "Immunostains revealed that the tumor cells were positive for CDX2 (intestinal marker) and negative for CK20 and CK7." (PMID 40671972, 2025). "Specific genes downregulated in HG tumours which showed significantly higher promoter methylation included the developmental transcription factors CDX1, CDX2, GATA6, HNF1A, the marker of colonic differentiation, DPP4, and the markers of LGR5+ intestinal stem cells, ASCL2, LGR5." (PMID 40473896, 2025). "At a median follow-up time of 51 months, the median OS was inferior for patients with CDX2-negative tumours (N = 27) when compared with those with CDX2-positive CRC (N = 319): median 30 versus 53 months, respectively (Mantel-Cox log-rank test, p = 0.008)." (PMID 38439814, 2024). "Immunophenotypically, the analysis of the tumor specimen revealed a strong expression of CDX2 and the absence of PAX8 expression, while only sporadic elements exhibited CK20 expression." (PMID 38732303, 2024).
tumor (continued). "The classification of CDX2 staining disclosed 27 patients (7.8%) whose tumours lacked CDX2 expression and 319 (92.2%) with CDX2-positive tumours." (PMID 38439814, 2024). "Patients with CDX2-negative tumours additionally had a faster progression on first-line treatment than those with tumours that expressed CDX2." (PMID 38439814, 2024). "While some studies classified as negative the complete absence of CDX2 IHC expression, other studies considered samples as negative when there was weak nuclear expression in less than 10% tumour cells." (PMID 38439814, 2024). "In our cohort the histopathological classification of grade 3 was more frequent in CDX2-negative tumours (20%) than expected (7.8%; p < 0.01), as observed by previous studies and linked to a poor prognosis in mCRC." (PMID 38439814, 2024). "In addition, among the enriched TFs in NN-HF, we further identified NFκB-P65, FOXA3, FOXD3, SIX1, CDX2, and MEF2C which have been found to impact tumor progression." (PMID 38720110, 2024). "Concerning the primary tumor site, research suggests that tumors exhibiting diminished or negative CDX2 expression are commonly found in the right colon, including the cecum, ascending colon, and transverse colon." (PMID 38786321, 2024). "Furthermore, the increased expression of Cdx2, and other differentiation-driving transcription factors like Klf4 and the WNT antagonist, Ndrg1, in BLM tumors push the tumor stem cells toward the various differentiated lineages." (PMID 38893159, 2024). "Inferior OS was also observed for patients with CDX2-negative (N = 8) compared to CDX2-positive (N = 157) tumours when adjusted to exclude samples with the BRAF p.V600E variant (median 18 versus 103 months, respectively; Mantel-Cox log-rank test, p = 0.043)." (PMID 38439814, 2024). "Last but not least, emerging findings suggest that the CDX2 gene acts as a tumor suppressor, hindering tumor cell growth and spread by interfering with the Wnt/β-catenin signaling pathway." (PMID 38786321, 2024). "The immunohistochemical analysis was essential in confirming the diagnosis, with the tumor showing positive staining for CDX2 and negative for CK7, CK20, and PAX-8." (PMID 39434934, 2024). "In our study, CDX2-negative samples had none or weak nuclear staining in up to 10% of tumour cells, whereas CDX2-positive tumours had moderate or strong staining." (PMID 38439814, 2024). "The lesion was strongly and diffusely positive for synaptophysin; most tumor cells showed moderate intensity of CDX-2 expression, while CK20 showed no immunoreactivity at all." (PMID 39036209, 2024). "Interestingly, we showed that knocking down Cdx2 significantly reduced the expression of differentiated lineages-related genes such as Muc2, Atoh1, and Guca2a in BRAF mutant tumor-derived organoids." (PMID 38893159, 2024). "Similarly, enriched LOH events covered tumour suppressor genes such as APC (5q22.2), ATM (11q22.3), and CDX2 (13q12.2)." (PMID 39461959, 2024). "This tumor stained positively for CK7 and CA19-9 and negatively for CK20 and CDX2." (PMID 37404765, 2023). "From a practical point of view, if CDX2 is expressed, an intestinal origin is more likely, suggesting the need for endoscopic procedures including VCE and DBE in order to find the primary tumor, the latter also allowing to achieve histological confirmation." (PMID 37685605, 2023). "Immunohistochemically, the tumor cells are positive for Hep Par-1 and arginase-1 and negative for CK 19 and caudal-type homeobox 2 (CDX2)." (PMID 37761023, 2023). "differential diagnosis of metastatic SRCC from secondary or metastatic SRCC; CDX‐2 (with no expression), villin, and β‐catinin (with low expression) exclude the gastrointestinal origin of the tumor." (PMID 36779496, 2023).
tumor (continued). "Regarding tumor stage, cases with advanced depth of invasion (pT4) demonstrated a tendency towards a loss of MUC5AC and CDX2 but not MUC2." (PMID 37240039, 2023). "Therefore, immunohistochemical workup, with different tumor markers including CK20, CDX2, and CK7 staining, is needed." (PMID 36291953, 2022). "Studies on a nude mouse subcutaneous tumor model have also shown that the overexpression of CDX2 and let-7b or the knockdown of COL11A1 could effectively reduce the volume and weight of the tumor." (PMID 35847935, 2022). "Consistent with the primary tumor, the PDX, PDO, and PDC models positively express ICC markers CK7, CK19, and CA19-9 and do not express markers of alternative differentiation (CK20 and CDX2)." (PMID 36274097, 2022). "Immunohistochemistry for the tumor cells was positive for pancytokeratin and cytokeratin 7, partially positive (up to 20%) for cytokeratin 20 and CDX2, and negative for estrogen receptors, monoclonal carcinoembryonic antigen (CEA), and synaptophysin." (PMID 35664390, 2022). "Immunohistochemical stains showed the tumor cells to be positive for CDX2, CK20, and SATB2 and negative for p63, GATA3, CK7, and Uroplakin II, indicating the colorectal origin of the tumor." (PMID 35178262, 2022). "Immunohistochemical assays showed that the tumor was positive for CK7, CDX-2, C-MET, and villin." (PMID 36212391, 2022). "Even though CDX2 is a specific marker, it is not positive in all cases and its expression can be affected by various factors, such as tumor type and evaluation methods." (PMID 35328309, 2022). "Our main hypothesis states that the expression of CK7, Napsin-A, TTF1, CK20, CDX2, and SATB2 in lung tumours is dependent on the tumour’s site of origin." (PMID 35027072, 2022). "CDX2 is absent in around 10% of CRC cancers, and CDX2-negative tumours are often associated with several adverse prognostic features, such as advanced stage, vascular invasion, poor differentiation, right-sided location, CIMP, and BRAF mutation." (PMID 34940086, 2021). "Ectopic expression of PTEN significantly diminished tumour cell invasion as well as Akt phosphorylation and EMT marker proteins induced by CDX2 knockdown; conversely, knockdown of PTEN recovered the tumour-suppressive effect of CDX2 overexpression." (PMID 33239678, 2021). "No significant survival differences were observed between CDX2-high vs CDX2-low/absent tumours within the different tumour budding/WHO grade subgroups." (PMID 34616012, 2021). "Tumor cells were cytokeratin 7 negative but cytokeratin 20, CDX2, and carcinoembryonic antigen (CEA) positive." (PMID 34514560, 2021). "Histological features such as tumour budding, perineural invasion, apical lymph node involvement, lymph node yield, lymph node ratio, and molecular features such as MSI, KRAS, BRAF, and CDX2 may assist in prognostication and optimising adjuvant treatment." (PMID 34940086, 2021). "Compared to CDX2-high neoplasms, CDX2-low/absent CRCs were also more frequent in high-grade CRCs according to the WHO grade and tumours with intermediate (Bd2) or high (Bd3) tumour budding activity as well as in MSI-H CRCs (P < 0.001, respectively)." (PMID 34616012, 2021). "The results of tumour xenografts in nude mice revealed that size of subcutaneous tumours was noticeably enhanced in MTX‐treated mice treated with miR‐24‐3p mimic, which was abrogated after CDX2 overexpression." (PMID 33621425, 2021). "On immunohistochemistry, the tumor cells show positivity for CEA, CK20, CDX-2, and CK7." (PMID 34307234, 2021). "The inhibition of miR- 221 and − 222 could increase p27Kip1 and CDX2 in EAC cells and decrease tumour growth in vivo." (PMID 35006466, 2021).
tumor (continued). "Super-TDU could specifically target YAP/VGLL4 tumor cells with a high ratio, reduce the endogenous YAP-TEAD interaction, and down-regulate the expression of target genes such as CTGF, CCN1, and caudal type homeobox 2 (CDX2) 110,111." (PMID 34539895, 2021). "Our in vitro and in vivo data consistently indicate that CDX2 induces the migration and infiltration of NK cells, increases the secretion of IFN‐γ and TNF‐α by NK cells, enhances NK cell toxicity against HNSCC, and suppresses the tumour growth in mice." (PMID 33733587, 2021). "Exploratory analyses suggested that the benefit from chemotherapy in the RCC2-low subgroup was independent of CDX2 expression, but the number of tumours with low CDX2 expression was too small to draw a firm conclusion." (PMID 33219056, 2020). "The tumor cells of metastatic rectal adenocarcinoma were positive for gastrointestinal markers CDX2, CK20 and Villin but were negative for TTF-1 and PAX8." (PMID 32375670, 2020). "The univariate analysis showed that only CDX2 expression was related with prognosis of BRAFV600E mutation patients, while gender, age, tumor location, tumor mutational burden (TMB) level and TNM stage were not." (PMID 33330032, 2020). "Delivery of miR-181d-5p via CAF sEVs promoted cell proliferation, invasion, migration, EMT, and inhibited cell apoptosis, through repression of CDX2 and HOXA5; in vivo study showed CAF mediated delivery of miR-181d-5p mimic increased tumor growth rate, volume, and weight." (PMID 32957712, 2020). "We assessed by microscopy the tumour-stroma ratio (TSR) and the immunohistochemical CDX2 intensity." (PMID 30847807, 2019). "Concerning about the origin of p63/p40 and CDX2, it was suggested that the tumor cells were not derived from ectopic squamous epithelium but from intestinal metaplasia." (PMID 30890174, 2019). "In this study, liver markers (AFP, Hepatocyte, Glypican-3, and GS) and colon markers (CK20, CAD17, CDX2, β-catenin, and SATB2) were used for staining of xenograft-derived tumours, with the result that all markers were either expressed only weakly, or were not express at all." (PMID 31367188, 2019). "Immunohistochemical analysis revealed that these tumor cells were positive for Caudal-type homeobox-2 (CDX-2) and negative for synaptophysin and chromogranin A. These findings suggested that the SMT originated from a gastrointestinal adenocarcinoma." (PMID 30776584, 2019). "CDX2 testing does not appear to provide additional prognostic or predictive information in the management of dMMR tumours." (PMID 30511046, 2018). "Based on the current results, however, reconsideration should perhaps be paid to patients with CDX2-negative tumours, since this group also demonstrated rather poor prognoses (5-year DFS of 68%)." (PMID 30425348, 2018). "The tumor cells were focally positive for cytokeratin (CK) 20 and Cdx2 (caudal type homeobox 2) and negative for CK7." (PMID 29933751, 2018). "The frequency of CDX2-negative, moderate and positive tumours in both cohorts combined was 10%, 27%, and 63%, respectively." (PMID 30425348, 2018). "It is often difficult but important to distinguish between an adenocarcinoma of the bladder from a colorectal origin because these two tumours have the same morphological appearance and immunohistochemical profile (CK7−/CK20+/CDX2+), while the therapeutic management is different." (PMID 29621151, 2018). "Based on the current results, patients with negative CDX2 expression in their tumours seem to be the group of clinical interest, and the group with a moderate score should likely be handled in the same way as patients with CDX2-positive tumours." (PMID 30425348, 2018). "This should preferably be a phase III study including patients resected for stage II disease, and with negative CDX2 expression in the tumour, to +/− adjuvant chemotherapy." (PMID 30425348, 2018).
tumor (continued). "SATB2 appears to be a more sensitive marker than CDX2 but its expression in the dMMR tumour group is not really known outside medullary carcinomas." (PMID 29621151, 2018). "Further studies with a large sample size are necessary to elucidate the impact of chemotherapy or tumor progression in CDX2-negative CRCs and confirm our findings." (PMID 29682204, 2018). "ANXA10 expression was not seen in any of the mucin-rich tumor components, where only Cdx2 inactivation was present and BRAFV600E expression was absent." (PMID 28072391, 2017). "Immunohistochemical examination of this tumor revealed positive staining for Cytokeratin 20, Mucin 2, and CDX2, although Cytokeratin 7 and Mucin 6 were negative." (PMID 28503335, 2017). "Moreover, FOXA1, FOXA2, and FOXA3 were also grouped together with the tumor/invasion suppressor genes EPHB2 and EPHB3, and with the intestine-specific differentiation genes CDX1 and CDX2 (cluster 2)." (PMID 29155818, 2017). "In the present case which is non-matching as MANEC, the adenocarcinoma component of the primary tumor and the intestinal metaplasia lesions were positive for CDX2 but the neuroendocrine cells were not." (PMID 27842605, 2016). "In total, 43.4 % of patients showed less than 50 % CDX2 positive tumor nuclei, and of those 14.4 % showed a close to complete lack of CDX2 expression (<5 % positive cells)." (PMID 27411517, 2016). "RT-PCR analyses of fresh frozen tumor tissue verified that tumors with a high expression of SOX2 had low or absent expression of CDX2." (PMID 27411517, 2016). "CDX2 and villin immunostains were also positive; thrombomodulin was positive in tumor vessels but not within the tumor cells themselves." (PMID 27006847, 2016). "Tumor cells of scalp nodules were positive for CDX2, but negative for TTF-1 and CK20 in this case; therefore, scalp nodules were not MCC and originated from the colon." (PMID 24884973, 2014). "In this report, tumor cells showed positive reaction for E-ca, CDX2 and MUC1, and negative reaction for MUC2, Hep Par1 and TTF-1." (PMID 23938020, 2013). "To further establish the robustness of RNAscope, we showed that CDX2-expressing tumor cells were positively stained by RNAscope while CDX2-negative adjacent normal gastric epithelial cells were not stained." (PMID 24340024, 2013). "Herein, we show that negative SMARCB1/INI1 expression (11% of CRCs) associates with loss of CDX2, poor differentiation, liver metastasis and shorter patients’ survival regardless of the MMR status or tumor stage." (PMID 24286138, 2013). "Additionally, the tumor cells showed diffuse positive reaction to CK20, CDX2 and CEA which is characteristic of intestinal epithelial cells, and frequent occurrence of goblet cells in the epithelium." (PMID 23044077, 2012). "Cdx-2 is a transcriptional factor crucial to the normal proliferation and differentiation of intestinal epithelial cells, however little is known about the transcriptional program that controls genes involved in NSCLC tumor growth." (PMID 22824143, 2012). "Of interest, role of Cdx2 transcription factor in the regulation of colon carcinogenesis remain controversial and studies suggest its role as a positive or negative ‘tumor modulator’." (PMID 22719836, 2012). "In this study, CDX2 pCTC was chosen to be examined with three objectives because CDX2 is both a sensitive and specific marker of intestinal differentiation and it is overexpressed in CRC tumour cells when compared with normal intestinal epithelium." (PMID 21364588, 2011). "In the present study, CDX2 negativity and cytokeratin 20 negativity suggested a non-colorectal origin of the tumor, rather than a colorectal malignancy." (PMID 22074191, 2011). "As the detection rate of CK20-positive circulating tumour cells (CK20 pCTCs) in CRC was only 62%, we aimed to improve the sensitivity for CRC by detecting another intestinal-type differentiation marker, CDX2 pCTCs, using the same methodology." (PMID 21364588, 2011).